ELN-AS1 (ELN antisense RNA 1)
Synonyms: CTB-51J22.1
Gene: Long non-coding RNA gene on chromosome 7 (74,058,905 to 74,062,308, reverse strand). Ensembl gene ENSG00000232415.
Diseases named in the same sentence as ELN-AS1 in open-access papers:
ELN-AS1 is named in the same sentence as 1 disease in open-access papers, as found by Europe PMC text mining. Sharing a sentence is not in itself a finding about the gene and the disease. The quoted sentences say what the papers report.
tumor (1 paper, 2021). "Nevertheless, the specific functions of ELN-AS1, AC103563.7, AF131215.5, LINC01871, AC08417.1, NRAV, AL049539.1, POC1B-AS1, AC108134.4, and AC019080.5 in the tumor microenvironment remain unknown." (PMID 34925511, 2021).